CD4 (CD4 molecule)
Diseases named in the same sentence as CD4 in open-access papers (continued):
Sharing a sentence is not in itself a finding about the gene and the disease.
AIDS (continued). "In stratified analysis, XRCC5 rs16855458 was significantly associated with CD4+ T cell counts in AIDS patients, whereas LIG4 rs1805388 was linked to the clinical phases of AIDS patients." (PMID 36312587, 2022). "Cryptococcosis is known to develop in patients with AIDS and idiopathic CD4 lymphopenia underlining the importance of CD4 T cells in the defense against Cryptococcus spp." (PMID 35425769, 2022). "In univariable analysis, APOL1 high-risk genotypes, West African ancestry, age, sex, prior AIDS, lower CD4 cell count, HIV viral load, anti– hepatitis C virus, diabetes, hypertension, and cardiovascular disease were associated with ESKD." (PMID 35497797, 2022). "We found that HIV transmission through a sexual contact (p = 0.0015), coinfection with HCV (p = 0.0147), diagnosis of AIDS (p = 0.0208) and age (p = 0.0076) were negatively associated with CD4 cells count, longitudinally evaluated." (PMID 36329104, 2022). "On one hand, it is a crucial driving force of the loss of CD4+ T cells, which contributes to the development of AIDS-related events such as opportunistic infections and cancer." (PMID 35967422, 2022). "After adjusting for CD4 cell count and history of AIDS diagnosis, hyperglycemia was significantly associated with all-cause and cause-specific mortality." (PMID 36301817, 2022). "This was surprising given the positive association between water insecurity and AIDS-defining illness, and that AIDS-defining illness is often related to CD4 count." (PMID 34373987, 2022). "HIV/AIDS patients with lower CD4 counts are more susceptible to cryptosporidiosis and have greater severity of disease." (PMID 36504775, 2022). "The primary aim of the present study was to explore the effect of ART initiation time, CD4+ cell counts, and other prognostic factors on AIDS-related death among a cohort of FPD using a competing risk model." (PMID 34592916, 2021). "The last theory employs that PLWH with low levels of CD4 cells are more likely to experience serious AIDS-defining events, therefore, creating a competitor risk with HL." (PMID 34831094, 2021). "On the other hand, a low CD4/CD8 ratio has been used as a biomarker for disease progression of several non-AIDS-associated pathologies, such as kidney disease, heart disease, neurocognitive disorders, among others." (PMID 34556049, 2021). "Factors associated with mean CD4 changes were analysed using repeated measures linear regression, and combined AIDS event and mortality were analysed using survival analysis." (PMID 34021711, 2021). "Severe immunodeficiency and/or HIV-related conditions prior to the initiation of ART, reflected by low CD4 counts or AIDS diagnosis, were associated with higher rates of discontinuation of first-line ART regimens in several previous reports." (PMID 33422112, 2021). "Several studies investigated the association between immunodeficiency and non-AIDS-related deaths; however, most of them showed the implication of the latest CD4 count or CD4 cell measurements shortly before death." (PMID 34886257, 2021). "After adjusting for pregnancy outcome, AIDS prior to delivery, CD4 and age at delivery and study site, this association was slightly attenuated (aOR = 0.58, 95% confidence interval [CI]: 0.35 to 0.97, p = 0.04)." (PMID 34021715, 2021). "An association was found between non-AIDS death causes and a longer time spent on cART as well as higher CD4 count at initiation of cART." (PMID 34886257, 2021). "MAC disease is an important acquired immune deficiency syndrome (AIDS)-defining opportunistic infection that typically occurs in HIV-infected individuals with CD4 counts of <50 cells/mm3." (PMID 34431951, 2021). "At the same time, there is a clear association between increased risk of death and male sex, low or missing CD4 cell count, prior AIDS, disseminated TB disease, weight loss and MDR-TB." (PMID 34615474, 2021).
AIDS (continued). "Our results demonstrate that patients with high CD4+ cell counts and late ART had a 9% higher risk of AIDS-related death than those with low CD4+ cell counts and early ART." (PMID 34592916, 2021). "It is noted that the expression of PD-1, LAG-3 and TIGIT in CD4+ T cells showed the strongest inverse associations with the number of CD4+ T cell from AIDS patients." (PMID 34578457, 2021). "HIV/AIDS is characterized by a progressive depletion of CD4 T cells, leading to a gradual deficiency in host immunity, along with increased susceptibility to opportunistic infections and, ultimately, death." (PMID 34017335, 2021). "The virus targets mainly T CD4+ cells and lead to AIDS (acquired immune deficiency syndrome) when their count is profoundly reduced." (PMID 34451871, 2021). "Patients who initiated ART within 90 days of HIV/AIDS diagnosis (sHR: 0.24, 95% CI: 0.22–0.27) or had baseline CD4+ counts of >500 cells/μL (sHR: 0.23, 95% CI: 0.19–0.28) were associated with lower AIDS-related mortality risk." (PMID 34592916, 2021). "On quantile regression analysis, calendar year of entry into care, and markers of more advanced HIV disease (higher viral load, lower CD4 cell count and clinical AIDS) were significantly associated with earlier ART initiation." (PMID 34006927, 2021). "Patients were stratified according to low or high risk factors of immune activation (low CD4 nadir, previous AIDS-defining condition or very-low-level viremia during follow-up)." (PMID 34458287, 2021). "This virus induces the lowering of CD4+ cell levels, making the body more vulnerable to all types of infections and causing acquired immunodeficiency syndrome (AIDS)." (PMID 34202941, 2021). "This study indicated risk of AIDS-related mortality decreased with an earlier ART initiation time after controlling for CD4+ cell counts and other confounders." (PMID 34592916, 2021). "HIV-1 can infect host CD4+ T cells and macrophages, resulting in CD4+ T cell loss and immune dysfunction that leads to the acquired immune deficiency syndrome (AIDS)." (PMID 33807824, 2021). "Clinical trials suggested that CsA treatment was associated with modest but transient increases in the CD4+ T count and delayed progression to AIDS." (PMID 34631899, 2021). "As AIDS and non-AIDS morbidity and mortality are determined by the state of CD4+T-cell loss, a fast restoration on CD4+T-cell levels during antiretroviral therapy (ART) is especially important." (PMID 34970271, 2021). "Inadequate dietary diversity contributes to micronutrient deficiency that lead to further HIV/AIDS progression and the reduction of CD4 count which increases risk of opportunistic infections." (PMID 34548547, 2021). "Our study results are consistent with previous studies that demonstrated individuals with current CD4 counts less than 200 cells/μL having a higher risk for developing new AIDS events/death after ART initiation." (PMID 34021711, 2021). "As a retrovirus, human immunodeficiency virus type 1 (HIV-1) can infect CD4-positive T-cells or macrophage, eventually causing acquired immunodeficiency syndrome (AIDS)." (PMID 33546092, 2021). "CXCR4 is the main coreceptor of HIV-1 in the later stages of infection, that leads to a decrease in CD4 cell count and is linked to a higher chance of advancing to the acquired immune deficiency syndrome (AIDS)." (PMID 34684878, 2021). "Patients with ART initiation time >1 year but CD4+ counts >350 cells/μL (sHR: 4.42, 95% CI: 3.30–5.91) had a higher AIDS-related mortality risk than those with ART initiation time >90 days but CD4+ counts ≤350 cells/μL (sHR: 4.33, 95% CI: 3.58–5.23)." (PMID 34592916, 2021). "The immunoprotective role of CD4+ T cells is underscored by their absence in individuals with AIDS, resulting in a high risk for developing disseminated fungal infections." (PMID 34880863, 2021).
AIDS (continued). "Untreated HIV-1 infection leads to a slow decrease in CD4+ T cell lymphocytes over time resulting in increased susceptibility to opportunistic infections (acquired immunodeficiency syndrome, AIDS) and ultimately death of the infected individual." (PMID 33953729, 2021). "Previous studies found associations between lower CD4 cell count, a history of AIDS-defining diagnoses, and higher peak viral load with compromised executive functioning." (PMID 34696375, 2021). "It is shown that patients dying from causes other than AIDS initiated cART at higher CD4 counts, had more experience in cART and were also rather treated near the time of death compared to individuals with AIDS-defining deaths." (PMID 34886257, 2021). "In contrast, people classified as RIC who had HIV-RNA loads > 200 copies/mL at the time of re-entry into care as a consequence of a decrease in the CD4 count during the gap in care had a higher risk of clinical progression, including new AIDS events." (PMID 33953250, 2021). "As such, chronic T cell activation has been linked to accelerated progression to AIDS and is suggested as an even better predictor of AIDS events compared to viral load and CD4+ T cell count in HIV infected individuals." (PMID 33836748, 2021). "Suboptimal CD4+ T-cell restoration is associated with increased AIDS- and non-AIDS-related morbidity and mortality (7, –, 10)." (PMID 33688002, 2021). "We previously characterized monocyte gene expression and inflammatory markers in 11 HIV-positive individuals on long-term ART (HIV/ART) at risk for non-AIDS complications because of low nadir CD4+ counts (median 129 cells/uL) and elevated hsCRP." (PMID 34447895, 2021). "There is a decisively increased risk of both serious AIDS and non-AIDS conditions for individuals who have either poor CD4 T-cell recovery or persistent inflammation." (PMID 34449812, 2021). "Lastly, data from a meta-analysis including 724 cases of intracerebral hemorrhage linked AIDS diagnosis and low CD4 with higher incidence of this event." (PMID 33670229, 2021). "CD4 lymphocytes have a major role in the suppression of OC, and as a result, AIDS patients with low CD4 lymphocyte counts are especially susceptible to Candida infections." (PMID 35004551, 2021). "Non-adherence to ARV therapy has shown to be associated with low CD4 count, high viral load, and risk of AIDS and death." (PMID 33737527, 2021). "Immune reconstitution inflammatory syndrome in AIDS patients can lead to an initial worsening of underlying diseases due to body's ability to mount a strong immune response after recovery of CD4 counts." (PMID 33768869, 2021). "Those patients who maintain low CD4+ counts remain at risk of acquired immunodeficiency syndrome (AIDS) progression, developing non-AIDS-related morbidity, and dying." (PMID 35115928, 2021). "The adjusted risk for progression to AIDS associated with a poor CD4+ recovery (discordant immunovirological response to treatment) was as high as 2.70 (95% CI 1.29–5.66) in some studies." (PMID 33670229, 2021). "Patients with CD4+ cell counts >350 who initiated ART after one year had 9% higher risk of AIDS-related death than those with CD4+ cell counts ≤350 whose ART initiation time was >90 days." (PMID 34592916, 2021). "Patients with high baseline CD4+ cell counts who initiated ART after one year had 9% higher risk of AIDS-related death than those with lower baseline CD4+ cell counts who initiated ART after 90 days but within one year of diagnosis." (PMID 34592916, 2021). "Previous AIDS or TB diagnosis, lower current CD4 count and adherence <95% were associated with combined new AIDS‐defining event and death." (PMID 34021711, 2021). "In fact, CD4+ cells play a central role in HIV/AIDS evolution since CD4+ count depletion has been linked to cellular immunity impairment and susceptibility to opportunistic infections." (PMID 34591866, 2021).
AIDS (continued). "Persistently heightened immune activation and inflammation on cART have been associated with both inefficient CD4 recovery and the onset of several non-AIDS defining conditions upon cART initiation." (PMID 34116650, 2021). "Patients were followed from baseline up to December 2019, to the development of a progression event (loss of VL control, CD4+ T cell decline, AIDS or death) or to the censoring date (lost to follow‐up or initiation of ART)." (PMID 33619912, 2021). "Clinical trials have also shown that the extract of Azadirachta indica leaves inhibits the invasion of human lymphocytes by HIV-I and causes a significant improvement in CD4+ cell number in a small number of patients with HIV/AIDS." (PMID 34257647, 2021). "A gap in care before ART initiation, calendar year of entry into care, and markers of more advanced HIV disease (higher viral load, lower CD4 cell count and clinical AIDS) were significantly associated with time of ART initiation at all quantiles." (PMID 34006927, 2021). "Patients at high risk for PCP, specifically HIV-infected patients with CD4+ T-lymphocyte counts of less than 200 cells/mm3 and all AIDS patients who have already had one or more episodes of PCP receive prophylaxis with TMP-SMX and aerosolized pentamidine." (PMID 32149364, 2020). "After adjusting for confounders in the multivariate analysis, oral hygiene, pregnancy, antibiotic used and CD4 level of the patient were significantly associated with oral candidiasis in HIV/AIDS patients." (PMID 32774600, 2020). "We concluded that, oral Candida colonization occurs more frequently in HIV/AIDS patients and are significantly more common in patients with CD4+ cell counts <200 cell/μl, thus placing them at higher risk of invasive infections caused by these pathogens." (PMID 32774600, 2020). "Levels of CD4+ lymphocyte have been found to not only provide useful information concerning the progression to AIDS and death but also identify those individuals at risk of neurocognitive impairment before more severe opportunistic infections occur." (PMID 32362864, 2020). "A CD4 cell count less than 200 cells/μl was a significant risk factor for acquiring oral candidiasis in HIV/AIDS patients (P<0.001)." (PMID 32774600, 2020). "Human immunodeficiency virus (HIV) causes acquired immunodeficiency syndrome (AIDS) by inducing cell death of T CD4+ lymphocytes." (PMID 33135539, 2020). "A low CD4:CD8 ratio has been linked to increased risk of non‐AIDS morbidity, independently of CD4+ T‐cell count." (PMID 32333726, 2020). "Suboptimal CD4+ T cell pool reconstitution in response to ART has been associated with a substantial increase in the risk of AIDS-related mortality and morbidity." (PMID 32579550, 2020). "Risk factors like low CD4 cell count, especially in the presence of clinical acute immunodeficiency syndrome (AIDS), protein S deficiency, and protein C deficiency, have demonstrated the strongest association with venous thromboembolism." (PMID 32704356, 2020). "After adjusting for confounders in the multivariate analysis, oral hygiene, pregnancy, antibiotic usage and CD4 level of the HIV/AIDS patients were significantly associated with oral candidiasis in HIV/AIDS patients." (PMID 32774600, 2020). "HAART has led to a reduction in the morbidity and mortality associated with HIV and AIDS due to its effectiveness in suppressing viral replication, plasma viral load, and improvements in CD4+ T cell counts." (PMID 33354483, 2020). "For AIDS patients, the factors associated with higher hospitalization expenses were longer hospital stay, CD4+ T cell count < 200 cells/μl, and more complications (P < 0.05)." (PMID 32867780, 2020). "Some studies in Brazil have linked BF recombinants with faster progression to AIDS-defining events or faster CD4+ lymphocyte count decline." (PMID 32218587, 2020).
AIDS (continued). "Early detection and treatment to control viral load levels and improve CD4 + T cell counts are integral steps to reducing the risk of AIDS complications, and are thus, an ideal way to reduce the economic burden on patients and their families." (PMID 32867780, 2020). "Progressive depletion of CD4+ T cell populations is one of the hallmarks of acquired immunodeficiency syndrome (AIDS) pathogenesis resulting in increased susceptibility to opportunistic infections and virus-associated malignancies." (PMID 33383959, 2020). "The acute phase of HIV infection is characterized by a substantial drop in peripheral CD4+ T cell counts while in the chronic phase, a continued decline of CD4+ T cells is associated with the development of AIDS." (PMID 33384690, 2020). "Firstly, the number of annually reported HIV and AIDS cases, as well as the number of cases linked with CD4 data are extracted from the HIV/AIDS information system in China." (PMID 32532238, 2020). "In progressive HIV disease, low CD4 count was associated with AIDS defining illness and increasing mortality, while untreated depression and poor ART adherence were independently associated with poorer CD4 outcomes." (PMID 32448151, 2020). "Previous studies have suggested that CRF01_AE is associated with faster AIDS progression (defined as CD4+ T-cell counts decreasing to < 200 cells/μl or < 350 cells/μl) compared to that with non-CRF01_AE10,11." (PMID 32985559, 2020). "The acute phase of HIV infection is characterized by a substantial drop in peripheral CD4+ T cell counts, while during the chronic phase, a slower and persistent decline of these CD4+ T cells is associated with the development of AIDS." (PMID 33384690, 2020). "Risk factors associated to oral candidiasis in HIV/AIDS patients in Kumba District Hospital: in the Bivariate analysis, brush mouth daily (oral hygiene) and CD4 cells/μl were significantly associated with oral candidiasis in HIV/AIDS patients." (PMID 32774600, 2020). "The loss of the CD4+ T population results in severe immunodeficiency characterised by susceptibility to infections and a certain type of infection-associated cancer (Kaposi sarcoma and B cell lymphoma), a syndrome known as acquired immune deficiency syndrome (AIDS)." (PMID 32708331, 2020). "The risk of experiencing a disease, mostly AIDS, for a patient with the lowest level of CD4 was higher than a patient with the highest level of CD4." (PMID 31996148, 2020). "A major hallmark of AIDS is the steady decline in the numbers of CD4+ T cells through a combination of cellular apoptosis, exhaustion, and subsequent immune system dysfunction." (PMID 33178456, 2020). "The lentivirus human immunodeficiency virus (HIV) targets and destroys CD4+ T cells, leaving the host vulnerable to life-threatening opportunistic infections associated with AIDS." (PMID 32075937, 2020). "Univariable analyses (not shown) suggested that older age, sex, ethnicity, mode of acquisition of HIV, HCV infection, HIV viral load, CD4+ T cell count, and CD4:CD8+ T cell ratio were associated with the development of a new AIDS event." (PMID 32664736, 2020). "An increased frequency of toxoplasma encephalitis, caused by Toxoplasma gondii, has been reported in AIDS patients, especially in those with CD4+ T cell counts <100 cells/μL." (PMID 32443329, 2020). "This study uncovered unavoidable indicative features (Age, WHO AIDS stages, Gender and Residence) as associated factors to CD4 count and VL decline." (PMID 34394214, 2020). "Most recent CD4+ T cell count [>500 vs. ≤200 cells/mm3: adjusted rate ratio 0.24 (0.16–0.34)] and CD4+:CD8+ T cell ratio [>0.8 vs. <0.2: 0.33 (0.21–0.52)] were independently associated with a new AIDS event." (PMID 32664736, 2020). "And studies showed that low CD4+ cell count (baseline CD4 count ≤ 50 cells/μL) was related to treatment failure, a lower CD4+ cell count was always associated with a higher risk of a new AIDS events or death." (PMID 32680536, 2020).